RNU7-130P (RNA, U7 small nuclear 130 pseudogene)
Gene: Small nuclear RNA gene on chromosome 5 (35,632,963 to 35,633,024, reverse strand). Ensembl gene ENSG00000238441.
Homologues: Orthologues: chimpanzee U7 (100% identical), macaque U7 (89% identical). Paralogues in human: RNU7-37P (85% identical), RNU7-97P (84% identical), RNU7-120P (82% identical), RNU7-35P (82% identical), RNU7-40P (82% identical), RNU7-48P (82% identical), RNU7-70P (82% identical), U7 (82% identical), RNU7-123P (81% identical), RNU7-124P (81% identical), RNU7-18P (81% identical), RNU7-19P (81% identical), and 142 more.